CACYBP (calcyclin binding protein)
Diseases named in the same sentence as CACYBP in open-access papers (continued):
Sharing a sentence is not in itself a finding about the gene and the disease.
bladder cancer (7 papers, 2020 to 2026). "CacyBP is an oncogene associated with bladder cancer, and the inhibition of CacyBP by the dCas9‐KRAB system can be a therapeutic approach." (PMID 37356052, 2023). "In conclusion, we have developed and validated a novel tumor-specific T cell signature (including VAMP5, TIGIT, LCK, CD27, and CACYBP) as a prognostic biomarker for bladder cancer patients treated with immunotherapy using single cell multi-omics data." (PMID 39033098, 2024). "We developed a five-gene signature (including VAMP5, TIGIT, LCK, CD27 and CACYBP) based on tumor-specific T cell-related genes to predict the immunotherapy response in bladder cancer patients." (PMID 39033098, 2024). "In our present study, we found that CacyBP expression was significantly upregulated in bladder cancer tissues compared with adjacent normal tissues." (PMID 34179100, 2021). "To explore the expression patten of CacyBP in bladder cancer tissues, we firstly checked its expression level in TCGA database." (PMID 34179100, 2021). "We measured the expression level of CacyBP in bladder cancer cell lines and found it was upregulated in bladder cancer cell lines (T24, UMUC3, BIU-87 and 5,637) compared to normal urothelial cells (SVHUC-1)." (PMID 34179100, 2021). "From our previous RNA-seq data of bladder cancer tissues, we found the mRNA levels of CacyBP were upregulated in bladder cancer tissues compared to normal tissues." (PMID 34179100, 2021). "Taken together, these results provide novel insight into how CacyBP regulate bladder cancer tumorigenesis and provide a potential therapeutic target for bladder cancer." (PMID 34179100, 2021). "CRISPR/dCas9-KRAB targeting CacyBP inactivates its expression and suggested its potent oncogenous function in bladder cancer through a serious of in vitro experiments." (PMID 34179100, 2021). "Then we examined the cell proliferation and migration ability after CacyBP downregulated through a serious of in vitro experiments in T24 and 5,637 bladder cancer cells." (PMID 34179100, 2021). "We further detected the expression levels of CACYBP in bladder cancer tissues and normal adjacent tissues of 50 patients with various grades, stages and T-stages in vivo." (PMID 32570217, 2020). "Furthermore, Kaplan-Meier survival analysis revealed that the higher expression of VAMP5, TIGIT, LCK, CHORDC1, CD27, and CACYBP was correlated with better outcomes in bladder cancer patients treated with immunotherapy." (PMID 39033098, 2024). "Then we used CRIPSR/dCas9-KRAB to knock down CacyBP in T24 and 5,637 bladder cancer cells." (PMID 34179100, 2021). "Besides, we further evaluated the migration ability after downregulated CacyBP in bladder cancer cell lines checked by wound healing and transwell migration assays." (PMID 34179100, 2021). "Next, we determined whether the downregulation of CacyBP inhibited bladder cancer cells proliferation." (PMID 34179100, 2021). "Collectively, the expression level of CacyBP is frequently increased in bladder cancer." (PMID 34179100, 2021). "This study demonstrated that CacyBP expression was increased in bladder cancer tissues and cell lines, and CacyBP may be involved in the regulation of malignant biological behavior of bladder cancer." (PMID 34179100, 2021). "For instance, Knocking down CACYBP inhibits the proliferation and migration of bladder cancer cells and promotes apoptosis through the caspase‐3/ELISA pathway, suggested that CACYBP may be an oncogene in bladder cancer." (PMID 41505248, 2026). "The results showed that the proliferation and migration ability of T24 and 5,637 bladder cancer cells was decreased after transfected with dCas9-KRAB and sgRNAs targeted CacyBP." (PMID 34179100, 2021). "We found the expression levels of CacyBP were downregulated after transfected with dCas9-KRAB in T24 and 5,637 bladder cancer cells." (PMID 34179100, 2021).
bladder cancer (continued). "Therefore, our study aimed to investigate the role of tumor-specific T cells in bladder cancer immunotherapy by constructing TstcSig, consisting of five tumor-specific T cell-related genes: CD27, CACYBP, TIGIT, LCK, and VAMP5." (PMID 39033098, 2024).
breast cancer (6 papers, 2012 to 2025). A primary or metastatic malignant neoplasm involving the breast. "One of them shows that expression of CacyBP/SIP is significantly decreased in breast cancer tissues, whereas the other demonstrates that CacyBP/SIP expression is increased in this tumor." (PMID 22926504, 2014). "This approach allowed us to monitor CacyBP/SIP expression at different stages of breast cancer development and we found, using this model, that CacyBP/SIP is up-regulated during carcinogenesis." (PMID 22926504, 2014). "Application of such a model allowed us to monitor changes in CacyBP/SIP level during development of breast cancer." (PMID 22926504, 2014). "In breast cancer, CACYBP knockdown has been shown to increase proliferation and invasion by upregulating COX-2, though other studies suggest that CACYBP expression may actually facilitate breast cancer progression." (PMID 40167359, 2025). "Interestingly, in breast cancer and glioma, the CacyBP/SIP expression profiles reported by different teams were completely opposite." (PMID 34179100, 2021). "Increase in CacyBP/SIP expression during development of breast cancer, observed early in the mammary tissues with only minimal pathological changes, might suggest an important role of this protein in the process of carcinogenesis." (PMID 22926504, 2014). "One group indicated that a lower level of CacyBP/SIP was present in the tumor tissue in comparison to the control one and, moreover, reduction in CacyBP/SIP expression was associated with poor prognosis of breast cancer patients." (PMID 22926504, 2014). "A related action on cytoskeleton could be exerted by CACYBP, although the results for its implication in breast cancer are seemingly contradictory." (PMID 22347440, 2012). "Conversely, CACYBP appears to function as a negative regulator of cell proliferation in astrocytoma and renal cell carcinoma, and may serve as a tumor suppressor in breast cancer." (PMID 40167359, 2025). "In this work we analyzed the level of the CacyBP/SIP protein and its mRNA in rat mammary cancer samples using immunohistochemistry, Western blotting, and RT-PCR." (PMID 22926504, 2014).
neuroblastoma (6 papers, 2013 to 2022). Neuroblastoma (NB) is the most common solid, extracranial childhood tumor. "Overexpression of S100A6 in neuroblastoma NB2a cells inhibits CacyBP/SIP complex activity, and consequently lowers the rate of tau dephosphorylation." (PMID 31156365, 2019). "Previous studies in neuroblastoma cell lines have suggested that CacyBP/SIP is present in the cytoplasm and translocates to the perinuclear region or to the nucleus after elevation of intracellular Ca2+ concentrations [Ca2+]i." (PMID 29534068, 2018). "Indeed, our experimental data confirmed that CacyBP/SIP was sumoylated in neuroblastoma NB2a cells, and moreover, we identified a lysine residue involved in this modification." (PMID 24078263, 2013). "A particularly high level of CacyBP/SIP was shown in brain as well as in neuroblastoma NB2a and pheochromocytoma PC12 cells." (PMID 24078263, 2013). "Ubc9-HA and CacyBP/SIP-3xFLAG were transiently overexpressed in mouse neuroblastoma NB2a cells and proteins from the cell extract were incubated with anti-FLAG M2 affinity resin to isolate CacyBP/SIP-3xFLAG with its targets." (PMID 24078263, 2013). "Recent studies have indicated that CacyBP/SIP participates in many cellular processes such as regulation of the ERK1/2 pathway, organization of the tubulin-actin cytoskeleton, differentiation of neuroblastoma cells and cardiomyocytes, and regulation of apoptosis." (PMID 22926504, 2014).
colorectal cancer (5 papers, 2016 to 2023). A primary or metastatic malignant neoplasm that affects the colon or rectum. "In colorectal cancer, CacyBP/SIP has been shown to reduce proliferation while enhancing the invasion and migration of cancer cells." (PMID 33330038, 2020). "Calcyclin Binding Protein/(Siah-1 interacting protein) (CacyBP/SIP) acts as an oncogene in colorectal cancer." (PMID 29534068, 2018). "Abnormal CacyBP/SIP levels have been found in pancreatic cancer, gastric cancer, colorectal cancer, osteogenic sarcoma, melanoma, kidney cancer, breast cancer, brain cancer." (PMID 33330038, 2020). "It has been shown that, depending on the type of cancer, CacyBP/SIP may act as a tumor suppressor (e.g., kidney, gastric cancer) or oncogene (e.g., pancreatic, colorectal cancer)." (PMID 37373509, 2023). "Thus, the effect of S100A6 modulation of CacyBP/SIP translocation on the function of tumorigenesis, especially in colorectal cancer, is worthy of future studies." (PMID 29534068, 2018). "In colorectal cancer, a study found that the expression of CACYBP was increased in three different primary CRC cell lines and significantly decreased its adhesion and β-catenin levels, suggesting that CACYBP/SIP may be related to CRC metastasis." (PMID 34179100, 2021).
melanoma (4 papers, 2018 to 2021). A malignant, usually aggressive tumor composed of atypical, neoplastic melanocytes. "About calcyclin binding protein, it is highly expressed in several type of cancer, including melanoma." (PMID 30241282, 2018). "In addition, studies have confirmed that CacyBP level increased in gastric, nasopharyngeal carcinoma, osteogenic sarcoma and melanoma." (PMID 33541291, 2021). "Increased levels of CACYBP/SIP protein were also found in gastric, colon, nasopharyngeal, osteosarcoma, and melanoma." (PMID 34179100, 2021).
glioma (3 papers, 2019 to 2025). A benign or malignant brain and spinal cord tumor that arises from glial cells (astrocytes, oligodendrocytes, ependymal cells). "On the other hand oncogene role of CacyBP/SIP was demonstrated in pancreas cancer and glioma." (PMID 33330038, 2020).
Huntington disease (3 papers, 2018 to 2020). Huntington disease (HD) is a rare neurodegenerative disorder of the central nervous system characterized by unwanted choreatic movements, behavioral and psychiatric disturbances and dementia. "Other neurodegenerative diseases, in which changes in CacyBP/SIP expression have been reported, include Parkinson’s disease (PD) and Huntington’s disease (HD)." (PMID 32492924, 2020). "Upregulation of CacyBP/SIP has been found in some neurodegenerative disorders such as frontotemporal dementia (FTD), amyotrophic lateral sclerosis (ALS) or Huntington’s disease (HD)." (PMID 33049998, 2020). "CACYBP has never been directly linked to ALS, nonetheless there are many indirect links with other neurodegenerative diseases like Huntington disease, PD and AD." (PMID 30577465, 2018).
multiple myeloma (3 papers, 2022 to 2025). "Furthermore, a study on multiple myeloma has reported that the exosome-derived AS factor SFRS8 regulates the AS of calcyclin binding protein (CACYBP) in the bone marrow microenvironment." (PMID 41268214, 2025).
renal cell carcinoma (3 papers, 2014 to 2023). "Increased CacyBP/SIP expression is also observed in renal cell carcinoma in which the up-regulation seems to be associated with suppression of cell growth and carcinogenesis." (PMID 22926504, 2014). "The same authors showed that injection of CacyBP/SIP mice led to reduced proliferative potential and carcinogenicity in cells overexpressing renal cell carcinoma." (PMID 37373509, 2023).
Alzheimer disease (2 papers, 2016 to 2017). A progressive, neurodegenerative disease characterized by loss of function and death of nerve cells in several areas of the brain leading to loss of cognitive function such as memory and language. "Moreover, CacyBP/SIP exhibits phosphatase activity towards tau protein, which suggests a possible role of CacyBP/SIP in Alzheimer’s disease pathology." (PMID 27249023, 2016). "Interestingly, it was found that S100A6 might influence the phosphatase activity of CacyBP/SIP towards tau, a protein involved in Alzheimer’s disease pathology." (PMID 28068373, 2017).
arterial hypertension (2 papers, 2023 to 2024). "In our previous studies, we also found an increased content of CacyBP/SIP in the heart of rats with arterial hypertension of various aetiologies, which suggests a role of this protein in hypertensive cardiac complications." (PMID 38780511, 2024). "The analysis of the obtained results showed lower expression of the gene encoding CacyBP/SIP in rats with spontaneous and secondary hypertension." (PMID 38203261, 2023). "The aim of this study was to comparatively evaluate the expression and localization of CacyBP/SIP and β‐catenin proteins, as well as CB1 and CB2 receptors in the adrenal glands of rats with arterial hypertension of various aetiologies." (PMID 38780511, 2024). "This is our previous study on the relationship between CacyBP/SIP protein and the MAPK pathway in hypertension of various aetiologies." (PMID 38780511, 2024). "The results of this study show, for the first time, marked differences in the expression of CacyBP/SIP, β‐catenin and CB1 and CB2 cannabinoid receptors in the adrenal glands of rats with primary (SHR) and secondary hypertension (2K1C)." (PMID 38780511, 2024). "The aim of the study is the comparative assessment of the expression of CacyBP/SIP, p-ERK1/2 and p-p38 in the adrenal glands of rats with primary and secondary hypertension." (PMID 38203261, 2023). "Future research in this area may also focus on further investigation of CacyBP/SIP-mediated signaling pathways and the establishment of selective inhibitors of CacyBP/SIP-mediated signaling to evaluate the prognostic and therapeutic values of hypertension." (PMID 38203261, 2023). "The obtained results may suggest the involvement of CacyBP/SIP in the regulation of signaling pathways in which MAP kinases play an important role and provide new insight into molecular events in hypertension." (PMID 38203261, 2023). "The interaction of recently discovered multifunctional protein-CacyBP/SIP with ERK1/2 and p38 kinases by regulating the activity and intracellular localization of these kinases may play an important role in the signaling pathways involved in the pathogenesis of hypertension." (PMID 38203261, 2023). "So far, there are no data on the cellular location and expression pattern of CacyBP/SIP, ERK1/2 and p38 in hypertension." (PMID 38203261, 2023).
astrocytoma (2 papers, 2020 to 2025). "Conversely, in astrocytoma patients, higher CACYBP expression is associated with a favorable prognosis, indicating a tumor-suppressive function." (PMID 40167359, 2025).
glioblastoma (2 papers, 2023). The most malignant astrocytic tumor (WHO grade IV). "Ubiquitination is an imperative post-translation process in eukaryotes, and CACYBP is recently suggested to suppress glioblastoma invasion and migration by modulating cytoplasmic p27 degradation and ubiquitination." (PMID 37305391, 2023).
liver cancer (2 papers, 2021 to 2025). An epithelial or non-epithelial malignant neoplasm that arises from the liver. "For example, in liver cancer, CACYBP promotes cell progression by modulating p27ˆKip1 and cyclins." (PMID 40167359, 2025). "Six genes (BIRC5, CACYBP, NR0B1, RAET1E, SPINK5, SPP1) were up-regulated in the liver cancer tissues compared to the normal tissues in the TCGA HCC dataset, and S100A8 was downregulated." (PMID 33568167, 2021).
myocardial infarction (2 papers, 2023 to 2024). Gross necrosis of the myocardium, as a result of interruption of the blood supply to the area, as in coronary thrombosis. "An increase in the level of CacyBP/SIP during myocardial infarction has also been demonstrated, which suggests a protective role of this protein for cardiomyocytes against hypoxia/reoxygenation." (PMID 38780511, 2024). "It has also been suggested that elevated levels of CacyBP/SIP may protect cardiomyocytes during myocardial infarction." (PMID 38203261, 2023).
bipolar disorder (1 paper, 2020). A disorder of the brain that causes unusual shifts in mood, energy, activity levels and the ability to carry out day-to-day tasks. "It is worth mentioning that global gene expression profiling using whole-genome microarrays has shown that CacyBP/SIP is up-regulated in another neurological disorder, that is, bipolar disorder (BD)." (PMID 32492924, 2020).
cervical cancer (1 paper, 2016). A primary or metastatic malignant neoplasm involving the cervix. "In order to test if FGFR2 and CACYBP play critical regulatory roles in cancer pathogenesis, we evaluated the effect onin vitro knockdown of these genes on cell proliferation in a cervical carcinoma cell line." (PMID 28163897, 2016). "In addition, we have tested two DC genes and confirmed their regulatory role (FGFR2 as a tumor suppressor and CACYBP as a potential oncogene in cervical cancer) by manipulating their expressionin vitro." (PMID 28163897, 2016). "Usingin vitro knockdown experiments for two out of 14 differentially co-expressed genes found in cervical cancer (FGFR2 and CACYBP), we showed that they play regulatory roles in cancer cell growth." (PMID 28163897, 2016). "Therefore, for validation experiments we chose one down-regulated (FGFR2) and one up-regulated (CACYBP) gene that have not been previously studied in cervical cancer for regulatory properties, but have a potential connection with cell death or proliferation based on their Gene Ontology annotations." (PMID 28163897, 2016).
clear cell carcinoma (1 paper, 2023). "CacyBP/SIP immunoreactivity in papillary and chromophobe RCC was similar to that in the control, but lower compared with clear cell carcinoma." (PMID 37373509, 2023).
complication (1 paper, 2020). Any disease or disorder that occurs during the course of, or because of, another disease, treatment, or procedure. "Our previous study showed an increase in CacyBP/SIP content in the heart of hypertensive rats of different etiology, which may suggest the involvement of CacyBP/SIP in hypertensive cardiac complications." (PMID 32119722, 2020).
COVID-19 (1 paper, 2024). A disease caused by infection with severe acute respiratory syndrome coronavirus 2. "CACYBP abundance was higher in the COVID-19 comparison group than that in the PQ comparison group." (PMID 39301288, 2024). "The expression of CACYBP, involved in the regulation of nonphosphorylation-dependent ubiquitination, was upregulated in the COVID-19 comparison group." (PMID 39301288, 2024). "Four DEPs (RAC1, CAMK2G, DAAM1, and RAC2) were enriched in the noncanonical Wnt pathway and two DEPs (TLE3 and CACYBP) were enriched in the canonical pathway in the COVID-19 comparison group." (PMID 39301288, 2024).
diabetes (1 paper, 2013). "There was a small (median differences = 0.01-0.04) but highly significant increase of DNA methylation in females compared to males in FBXL5 and CACYBP (p < 1.00E-04) and a trend towards significance for SCMH1 (p = 0.07), in the diabetes study where samples of both sexes were included." (PMID 23356856, 2013).
Down syndrome (1 paper, 2020). "Another brain disorder in which the expression of CacyBP/SIP seems to be up-regulated is Down syndrome (DS)." (PMID 32492924, 2020).
gastric tumors (1 paper, 2023). "Thus, in normal tissues such as the colon or stomach, the CacyBP/SIP protein is almost undetectable, while in colon or gastric tumors, it is highly expressed, and the level of expression is correlated with metastasis." (PMID 37373509, 2023).